STAT3 (signal transducer and activator of transcription 3)
Diseases named in the same sentence as STAT3 in open-access papers (continued):
Sharing a sentence is not in itself a finding about the gene and the disease.
lung carcinoma (continued). "Blockade of STAT3 signaling in lung cancer cells prevented lung metastasis in immune-competent syngeneic mice, but not in immune-deficient nude mice, which implies that STAT3-mediated immunosuppressive traits in tumor cells are functionally critical for lung metastasis in vivo." (PMID 33322216, 2020). "Previous studies suggested that IL-37 could inhibit the activation of the NF-κB and IL-6/STAT3 signaling pathway and suppressed the occurrence of the inflammatory response in Myasthenia Gravis (MG) by affecting Tfh and B cells, and in lung cancer by affecting A549 cells." (PMID 32733162, 2020). "Thus DDIAS may be considered as a potential biomarker and therapeutic target in malignant lung cancer cells with aberrant STAT3 activation." (PMID 31900385, 2020). "However, whether STAT3 plays a role in lung cancer cells treated by nicotine remains to be clarified." (PMID 31956373, 2020). "In addition, the effect of CHK9 on the activation of STAT3 in lung cancer cells was examined." (PMID 32967366, 2020). "The apparently contradicting results regarding STAT3 in lung cancer are entirely consistent with our hypothesis that the tumor suppressor function of STAT3 stems from its noncanonical function in controlling heterochromatin, i.e., uSTAT3 rather than pSTAT3 suppresses tumors." (PMID 32087696, 2020). "Therefore, we put forward the speculation that the knockdown of metastasis-related protein BRD4 could mediate the JAK2/STAT3 pathway and suppress the lung cancer cell migration and invasion." (PMID 31621555, 2020). "Therefore, our findings provides a valid evidence that FZKA might function as a STAT3 inhibitor when treat lung cancer patients." (PMID 32489321, 2020). "Therefore, targeting STAT3 signaling may provide significant clinical benefit in the treatment of STAT3-positive lung cancer patients." (PMID 32967366, 2020). "Additionally, CD109 acts as a metastatic driver in lung cancer via regulating JAK/STAT3." (PMID 33375719, 2020). "Therefore, we explored whether the downregulation of PTPRK leads to STAT3 activation in lung cancers." (PMID 30838170, 2019). "Inhibition of STAT3 activation may thus represent an effective approach to treat lung cancer." (PMID 30914735, 2019). "However, STAT3 is constitutively active in most lung cancers." (PMID 30838170, 2019). "Therefore, STAT3 activation induced by LDOC1 silencing may be associated with genetic abnormalities of EGFR and ALK and may exert a synergistic effect in lung cancer; this topic may be worth exploring in the future." (PMID 30634502, 2019). "In addition, because we demonstrated that STAT3 induced HER3 expression in EGFR-positive lung cancers, the inhibition of STAT3 could prevent HER3-mediated EGFR-TKI resistance." (PMID 31619200, 2019). "Moreover, PEITC anti-metastatic potential reported to be significantly increased after inhibition of autophagy and, subsequently, inactivation of the JAK2 (Janus kinase 2)/STAT3 (signal transducer and activator of transcription 3) pathway in three lung cancer cell lines." (PMID 31003534, 2019). "We determined whether KLF3 regulates STAT3 expression in lung cancer cells." (PMID 31486564, 2019). "Therefore, the decreasing activity of PTPRK may be partly accountable for the constitutive activation of STAT3 in lung cancers." (PMID 30838170, 2019). "In addition, STAT3 signalling is known to be a downstream target of miRNA‐3127 in lung cancer." (PMID 29726585, 2018). "To investigate whether PI3K/AKT and STAT3 signaling pathways were involved in ING5 knockdown-stimulated lung cancer invasiveness in vivo, we made intravenous mouse xenograft model by injecting A549 shControl and A549 shING5 cells through tail veins of nude mice." (PMID 28903339, 2017). "However, recent study also indicated that Stat3 could play tumor-suppressive role in K-ras mutant lung cancer as K-ras mutant lung tumors had reduced Stat3 levels." (PMID 28360411, 2017).
lung carcinoma (continued). "As such, pro-inflammatory cytokine signaling through JAK/STAT3 could be critical for the interactions between lung cancer cells and stromal cells in the transformation of lung cancer cells to take on stromal cell properties, which promote progression of lung cancer and result in poor prognosis." (PMID 28819126, 2017). "Indeed, treatment of lung cancer cells with TNF-related apoptosis-inducing ligand led to RIP1-mediated STAT3 activation resulting in increased cell invasion;24 RIP2-mediated activation of NF-κB was crucial for triple-negative breast cancer cell motility and invasion." (PMID 28574510, 2017). "However, it has recently been demonstrated that low STAT3 expression correlated with poor survival and advanced malignancy in human lung cancer patients with smoking history, and disruption of Stat3 signaling enhanced lung tumor initiation and malignant progression in mice." (PMID 29126425, 2017). "Thus, suppression of STAT3 phosphorylation might sensitize MDR-overexpressing lung cancer cells to paclitaxel." (PMID 29072615, 2017). "Besides its direct protumorigenic effects on tumor cells via STAT3/Akt pathways, IL-6 signaling has indirect effects by promoting an immunosuppressive tumor microenvironment, which has been described in a Kras-induced lung cancer mouse model." (PMID 28878242, 2017). "Furthermore, Stat3 plays a critical role not only in the TKI-resistant lung cancer, but also in other multi-drug resistant malignancy including non-Hodgkin's lymphoma, multiple myeloma, epidermoid cell skin carcinoma, prostate carcinoma, and even self-renewal of cancer stem cells." (PMID 27419630, 2016). "As KRAS is still considered as an undruggable target and is responsible for 30% of all Caucasian AC cases, we investigated whether STAT3 inhibition has a potential survival benefit in a preclinical lung cancer mouse model and in a human cell line xenograft model." (PMID 25734337, 2015). "STAT3 may upregulate expression of NF-κβ and has increased expression in lung cancer." (PMID 26220864, 2015). "In addition, we are the first to define the regulation of STAT3 and RAP1A by a single miRNA in the context of lung cancer, and provide the first preliminary evidence showing that STAT3 expression is an intrinsic determinant of paclitaxel response in lung cancer cells." (PMID 22723956, 2012). "Overexpressed STAT3 restored GMI-induced apoptosis and GMI-reduced transcription of CD47 in HCC827 and H1975 lung cancer cells." (PMID 41438583, 2026). "In lung cancer, CAFs are a major source of IL6 and CAF‐derived IL6 promotes metastasis via STAT3 signalling." (PMID 39743376, 2025). "In lung cancer, CITED4 is induced by heparin-binding epidermal growth factor (HB-EGF) through signal transducer and activator of transcription (STAT3)-dependent pathway, resulting in cell proliferation." (PMID 40389954, 2025). "In lung cancer and lymphoma models, AZD9150 has been shown to effectively reduce STAT3 activity and its downstream targets by decreasing STAT3 mRNA levels." (PMID 40166646, 2025). "This inflammatory microenvironment promotes bronchioalveolar stem cell growth and activates key signaling pathways such as nuclear factor-kappa B and signal transducer and activator of transcription 3 (STAT3), which are essential for lung cancer development." (PMID 40002883, 2025). "Endostar inhibited HIF-1 expression in A549 and NCI-H1299 lung cancer cells, upregulated expression of MHC class I α-heavy chain and β2 m light chain, with the upregulation of STAT3 and pSTAT3, suggesting involvement of STAT3 pathway." (PMID 40392714, 2025). "In lung cancer, TM4SF4 expression is upregulated where it promotes tumor growth, migration, and invasion through activation of PI3K/AKT and JAK2/STAT3 pathways, as well as preserving cancer stem cell features." (PMID 39999090, 2025). "The regulation of STAT3 by α5-nAChR serves as a mediator in modulating the expression levels of NLRP3, thereby affecting the progression of lung cancer." (PMID 40143965, 2025).
lung carcinoma (continued). "Five core protein targets, AKT1, EGFR, HSP90AA1, SRC, and STAT3, were identified as potential mediators of steamed PJR’s anti-lung cancer effects." (PMID 41465428, 2025). "Knockdown of STAT3 can block the secretory function of CAF, thereby reversing Osimertinib resistance in lung cancer." (PMID 40703348, 2025). "Experimental evidence supports the role of STAT3 and STAT6 in reducing tumor growth and metastasis in breast and lung cancer models." (PMID 39827422, 2025). "Pharmacological inhibition of IL-1R and STAT3 signaling effectively suppressed BM growth, highlighting the therapeutic potential of targeting the LCN2 axis in lung cancer brain metastasis." (PMID 41436606, 2025). "α5-nAChR via STAT3/Jab1 signaling cascade facilitates EMT and metastasis in lung cancer cells, accompanied by enhanced N-cadherin and vimentin expression." (PMID 40143965, 2025). "RES suppressed the inflammatory microenvironment, decrease the expressions of p‐NF‐ĸB, IL‐1β, IL‐8, and IL‐23, and inactivate the STAT3/VEGF signaling pathway, thereby reducing drug resistance in lung cancer cells." (PMID 40860906, 2025). "Other research has shown that overexpression of STAT3 promotes tumor sphere formation, and its inhibition by CUR halts lung cancer progression." (PMID 40860906, 2025). "It was shown that α5-nAChR regulates the expression of STAT3 and Jab1/Csn5, significantly modulates the expression of EMT markers, and affects lung cancer invasion and metastasis." (PMID 40143965, 2025). "Some studies propose that α5‐nAChR mediates nicotine‐induced lung cancer through activation of the JAK2/STAT3 signaling pathway, establishing the mutual interaction between α5‐nAChR and STAT3." (PMID 41218914, 2025). "In the context of lung cancer, APS suppresses the S1PR1/STAT3 signaling pathway, which reduces the premetastatic niche, a distant secondary microenvironment prepared for future metastatic growth, which is essential for preventing metastasis." (PMID 40149916, 2025). "Through these and other pathways (NF-κB, STAT3, PI3K/Akt, etc.), EV-delivered miRNAs orchestrate multiple aspects of lung cancer progression, including proliferation, invasion, immune suppression, and metastatic niche formation." (PMID 41311647, 2025). "Firstly, scutellarin induced cell cycle arrest, apoptosis and autophagy, and also inhibited migration and invasion of lung cancer and human leukemia cells through suppressing ERK, AKT and STAT3 signaling pathways." (PMID 39888904, 2025). "Upon uptake by lung cancer cells, miR-210-3p targets the SOCS1 gene, activating the STAT3 pathway by suppressing SOCS1 expression, thereby enhancing VEGF production." (PMID 39273095, 2024). "In brief, preclinical evidence reveals that targeting IL-6, STAT3, MAPK3, or AKT1 provides an effective way to suppress lung cancer." (PMID 39258670, 2024). "The CHRNA5 promoter harbours a binding site for STAT3, and nicotine induces the proliferation of lung cancer cells by enhancing CHRNA5 expression and activating the JAK2/STAT3 signalling cascade." (PMID 38879667, 2024). "The CHRNA5 promoter had four STAT3 response elements, and the interaction between CHRNA5 and STAT3 facilitates the nicotine-induced proliferation of lung cancer cells." (PMID 38879667, 2024). "A study provided evidence that the combination of zerumbone (Zer) and gefitinib (Gef) in lung cancer treatment downregulates p-Akt and p-STAT3, indicating the inhibition of the AKT/STAT3 signaling axis." (PMID 38562143, 2024). "In the present study, we found that PRMT5-mediated methylation is important for constitutive activation of STAT3, as well as for CSC maintenance and tumorigenesis in lung cancer cells." (PMID 38760429, 2024). "Another study that examined the anticancer potential of various cucurbitacin compounds in different cancer models found that CuI inhibited the activation of STAT3 and JAK2 in A549 lung cancer cells." (PMID 38397437, 2024).
lung carcinoma (continued). "The expression levels of the top five lung cancer genes, CTNNB1, STAT3, HIF1A, HSP90AA1, and ERBB2, were determined by comparing them with the LUAD and LUSC datasets using the GEPIA2 web server." (PMID 39113883, 2024). "In lung cancer cells A549 and H460, microarray analysis revealed that Slug is a downstream effector molecule of CXCR4/STAT3 signaling." (PMID 39195486, 2024). "Targeting specific proteins such as SRC, STAT3, PIK3CA, MAPK1, EGFR, and JAK1 is crucial for impeding the growth of lung cancer." (PMID 38921583, 2024). "As an upstream mediator of EMT, STAT3 can upregulate EMT expression in brain tumors, lung cancer and gastrointestinal cancer to mediate tumor metastasis and plays an important role in the development of various tumors." (PMID 38486162, 2024). "CDK1 is a potential prognostic biomarker and target for lung cancer; CDK1 activity is critical for JAK/STAT3 signaling activation, and the inhibition of CDK1 can suppress lung cancer." (PMID 38783288, 2024). "Clinical samples from lung cancer patients have demonstrated the co-expression of CXCR4, p-STAT3, and VEGF-A, suggesting a potential role in tumor progression and angiogenesis in non-small cell lung cancer (NSCLC)." (PMID 38920657, 2024). "On the contrary, other research has indicated that the interaction between aldo-keto reductase family 1 member B1 (AKR1B1) and STAT3 results in the upregulation of SLC7A11, which promotes ferroptosis resistance in lung cancer." (PMID 38485916, 2024). "In lung cancer, suppression of ATM enhanced the sensitivity of DDP and EMT progression via JAK/STAT3/PD-L1 pathway." (PMID 38993556, 2024). "IL-6 secreted by TAMs promotes lung cancer progression and metastasis in vivo and in vitro by activating the EMT pathway, which can be attenuated by the use of JAK2/STAT3 pathway inhibitors or IL-6 monoclonal antibodies." (PMID 38424624, 2024). "Clinical lung cancer tissue samples also reveal a positive correlation between elevated CXCL12 and positive p-STAT3 expression and the malignant progression of lung cancer." (PMID 38920657, 2024). "Mechanistically, CHRNA5 mediates the Stat3–Jab1–Csn5 and TGF-β1–Smad signalling pathways to promote the metastasis and EMT of lung cancer cells." (PMID 38879667, 2024). "IL6/STAT3 pathway is activated in KRAS-driven tumors and can contribute to tumor occurrence and drug resistance in lung cancer." (PMID 39191757, 2024). "Inhibiting STAT3 and FAK signaling pathways is considered a promising strategy for treating lung cancer." (PMID 39588118, 2024). "In our study, we found that a microenvironment with high IL-6 expression in lung cancer was able to activate the JAK2/STAT3 pathway in TAMs, and STAT3, a transcription factor, was able to promote C/EBPβ expression." (PMID 38424624, 2024). "In vitro studies showed that leptin enhanced production of soluble intercellular adhesion molecule-1 (ICAM-1) in lung cancer cells through triggering a signaling cascade involving JAK1/2, STAT3, FAK, ERK, and GSK3αβ." (PMID 38571500, 2024). "A study investigating apigenin as an anticarcinogenic agent in KRAS-mutant lung cancer cells revealed its ability to inhibit MUC1-C and PD-L1 expression, accompanied by the downregulation of STAT3 expression." (PMID 39690423, 2024). "Mechanistically, IGFBP2 stimulated the transcriptional activity of STAT3 on CXCL1, leading to an upregulation of CXCL1 expression in lung cancer cells and subsequently promoting gefitinib resistance." (PMID 38918360, 2024). "As STAT3 has been established as a key player in many types of cancer, a novel STAT3 ASO, known as AZD9150, is currently undergoing clinical investigation for the treatment of lymphoma and lung cancer." (PMID 38424137, 2024). "We conducted further investigations to examine the impact of STAT3 and ACC1 on the progression of lung cancer in vivo." (PMID 38495496, 2024).
lung carcinoma (continued). "The crucial role of STAT3 pathway in MEKi resistance is also supported by a recent study demonstrating the synergistic effect of STAT3i and MEKi in KRAS-mutant lung cancer." (PMID 39191757, 2024). "In another study, at a concentration of 2 μM, homoharringtonine inhibited the expression of KRAS, ERK, Akt, STAT3, CDK4, and CDK6 in A549 and H1299 lung cancer cells." (PMID 37568796, 2023). "N‐myristoylation of EZH2 promotes phase separation of EZH2 with its substrate STAT3, leading to the activation of STAT3 signaling and growth of lung cancer cells, making N‐myristoylation of EZH2 a potential target for lung cancer therapy." (PMID 37143582, 2023). "For example, lncRNA MALAT1 increases cisplatin resistance in lung cancer by enhancing the expression of MRP1 and MDR1 by activating the STAT3 pathway." (PMID 36778005, 2023). "Compared to the sham group, the expression of IL‐6, phosphorylated STAT3 and two major MAPKs subtypes (phosphorylated p38‐MAPK and phosphorylated ERK1/2) were significantly increased in the lung cancer model group." (PMID 37875398, 2023). "In lung cancer, physalin A was shown to decrease cell migration, angiogenesis, migration, and proliferation via the JAK/STAT3 signaling pathway in H292, H358, and H1975 cell lines." (PMID 37568796, 2023). "In lung cancer, specifically, homoharringtonine has been reported to decrease JAK1/STAT3 signaling at a concentration of 2–4 μM in A549 cells." (PMID 37568796, 2023). "Activation of Signal Transducer And Activator Of Transcription 3 (STAT3) signalling induced EMT and increased miR‐193a‐3p, miR‐210‐3p and miR‐5100 levels, prompting lung cancer metastasis." (PMID 37697969, 2023). "A novel signaling cascade, IL-6/STAT3/HIF-1α, has been discovered in numerous cancer types including pancreatic cancer, prostate cancer, lung cancer, colon cancer, and malignant glioma." (PMID 36814597, 2023). "Together, these results revealed that Q11 can inhibit the activation of the IL‐6/STAT3 pathway and the MAPK/ERK pathway in lung cancer." (PMID 37875398, 2023). "Inflammatory signaling pathways, such as nuclear factor-kappa B (NF-κB) and signal transducer and activator of transcription 3 (STAT3), are frequently activated in lung cancer." (PMID 38052753, 2023). "Silibinin, a polyphenolic flavonoid, is a direct inhibitor of STAT3, and it reverses ADR of crizotinib in ALK-rearranged lung cancer cells." (PMID 36902166, 2023). "STAT3 was highly expressed in BRCA, ccRCC, UCEC, lung cancer, HNSC, pancreatic cancer, and glioblastoma, but lowly expressed in ovarian cancer, colon cancer, and liver cancer." (PMID 37724127, 2023). "Another STAT3 inhibitor, TTI-101(C188-9) was shown to decrease tumor volume and growth in the A549 xenograft model of lung cancer and it has entered a phase I trial as an oral STAT3 inhibitor in patients with advanced cancers, including NSCLC (NCT03195699)." (PMID 36899885, 2023). "Treatment with erlotinib induced apoptosis of lung cancer HCC827, HCC827ER, and H1975 cells, but using both erlotinib with STAT3 siRNA significantly enhanced this effect." (PMID 38067351, 2023). "The activation of STAT3 is predominantly regulated by upstream JAK kinases in various cancer types, including lung cancer." (PMID 37894738, 2023). "The interactions between stromal cells and tumor cells activate various molecular signaling pathways, such as interleukin-6/STAT-3/c-Myc pathway, and TGF-β pathway in prostate cancer, lung cancer, and colorectal cancer." (PMID 37173640, 2023). "Apoptosis was also observed in action for CuB in cancer cells via inhibition of the IL-6/STAT3 pathway, via modulating the miR-17-5p/STAT 3, and for CuI via down-regulation of the PI3K/AKT/p70S6K pathway in lung cancer cells." (PMID 37887406, 2023).